NLRP3 (NLR family pyrin domain containing 3)
Diseases named in the same sentence as NLRP3 in open-access papers (continued):
Sharing a sentence is not in itself a finding about the gene and the disease.
bacterial infection (continued). "Given the critical role that NLRP3 activation plays in mounting an effective immune response to bacterial infection, it is not surprising that bacterial pathogens have developed tools to subvert inflammasome activation." (PMID 35663964, 2022). "However, inflammasomes including AIM2, NLRP3 and NLRC4 are also expressed in neutrophils and involved in IL-1β secretion during bacterial infection." (PMID 34017331, 2021). "Recent results with extracellular bacterial infections demonstrate that phagocytosed microbial RNA can be sensed by a combination of transmembrane PRRs such as TLR3 and cytosolic PRRs such as NLRP3 that cooperate to induce IL-1 and type I IFN for the regulation of Tfh responses." (PMID 33104760, 2020). "Our data emphasize the protective nature of NLRP10 against microbial pathogens, thus adding NLRP10 to the group of NLR family members such as NOD1, NOD2, NLRC4, NLRP3, and NLRP12 that initiate pro-inflammatory signaling to mediate host resistance toward bacterial infections." (PMID 29163529, 2017). "It was recently shown that there is cooperation between NLRP3 and NLRC4 inflammasomes in vivo during S. typhimurium infection, and that deficiency of either NLRP3 or NLRC4 does not change the bacterial infection in the mice." (PMID 22768222, 2012). "It is interesting to note that a major role for Syk in mediating NLRP3-dependent responses has not been reported for bacterial infections." (PMID 21740493, 2011). "Hence, in the absence of apoptotic signals, CL-mediated NLRP3 activation requires substantial mitochondrial damage or an intracellular bacterial infection." (PMID 38077364, 2023). "Conversely, relocalization of HK to the cytoplasm was shown to be important during bacterial infection, in which HK can physically detect the bacterial cell wall molecule N-acetylglucosamine and trigger the NLR family pyrin domain containing 3 (NLRP3) inflammasome independent of enzymatic activity." (PMID 31344128, 2019). "However, due to the diversity of these agonists, it is likely that NLRP3 does not bind directly to microbial PAMPs but instead detects cellular perturbation as part of a “Guard model”, similar to the detection of Rho GTPases by Pyrin after bacterial infection." (PMID 33925158, 2021). "However, published study reports that NLRP3 inflammasome-mediated pyroptosis occurs in diabetic rats following ischemic reperfusion injury within the heart where pyroptosis was not initiated by a bacterial infection." (PMID 31600901, 2019).
neurological diseases (120 papers, 2013 to 2026). "Activation of NLRP3-related signaling pathways has been implicated in various neurological disorders, including cognitive dysfunction." (PMID 40417311, 2025). "The NLRP3 inflammasome is linked to inflammatory and neurological disorders due to its inappropriate activation." (PMID 38421496, 2024). "The Nod-like receptor 3 (NLRP3) inflammatory vesicle pathway is a central point for initiating and maintaining neuroinflammation and is closely associated with various neurological diseases." (PMID 37670944, 2023). "To date, the NLR family pyrin domain containing 3 (NALP3), encoded by NLRP3 gene, is the most studied inflammasome as it has been found to be associated to various inflammatory, metabolic, and neurological diseases." (PMID 36680007, 2023). "Activation of the NLRP3 inflammasome is an important neuroinflammation marker, and its activation is associated with the occurrence and development of various nervous system diseases." (PMID 37636861, 2023). "Activation of microglial NLRP3 inflammasome is an essential contributor to neuroinflammation underlying HIV-associated neurological disorders (HAND)." (PMID 36812097, 2022). "Recent research has shown that phytochemicals in food can protect neurons from neurological diseases caused by the NLRP3 inflammasome by blocking the TLR4 axis pathway signaling pathway." (PMID 36015156, 2022). "The human immunodeficiency virus-1 envelope protein gp120 was found to cause neurological disease dependent on NLRP3-mediated pyroptosis." (PMID 35722622, 2022). "Activation of NLRP3 inflammasome is closely associated with neuronal damage in multiple neurological diseases." (PMID 35624482, 2022). "The NLRP3 inflammasome serves as an intracellular sensor for host-derived risk signals associated with neurological disorders." (PMID 33525754, 2021). "An in vivo model of feline immunodeficiency viral infection and HIV-1 Vpr transgenic mice exhibited NLRP3 inflammasome activation with accompanying neuronal loss and neurological disorders." (PMID 28337127, 2017). "Although hypouricemia has been associated with several neurological diseases, it has also been found that high levels of UA, which activates the NLRP3 inflammasome, are upregulated in the cerebrospinal fluid of MS patients." (PMID 24511458, 2013). "Notably, loss of the NLR family pyrin domain containing 3 (NLRP3), an inflammasome implicated in multiple neurological diseases, prevented the development of AD-related pathology." (PMID 37173751, 2023). "Indeed, NLRP3 is nowadays considered a promising therapeutic target for the treatment of neuroinflammation-associated neurological diseases." (PMID 29996878, 2018). "The present study focused on the NLRP3 inflammasome, the most extensively studied and clinically implicated inflammasome, which can be activated by a variety of dangerous signals, leading to sterile inflammatory responses involved in several neurological diseases." (PMID 29357878, 2018). "Finally, we conclude that NLRP3 inflammasome signaling may represent a promising therapeutic target for the treatment of neuroinflammation-associated neurological diseases." (PMID 28337127, 2017). "While all the inflammasome sensors NLRP1, NLRP3, NLRC4, AIM2, and pyrin have the capability to form canonical inflammasome complexes, the NLRP3 is the best studied in neurological disorders, being directly involved in pyroptotic neuronal death." (PMID 41486173, 2026). "The role of the NLRP3 inflammasome in neurological disorders has been confirmed by numerous studies." (PMID 40806374, 2025). "For example, synthetic steroid 5α-Androst-3β has been shown to inhibit the GBP5/NLRP3 axis, reducing microglial activation and pro-inflammatory cytokine release, thereby protecting neurons in neurological disorders." (PMID 40788157, 2025).
neurological diseases (continued). "The role of NLRP3-inflammasomes has been disclosed by many studies, suggesting that neuroinflammation is a relevant pathogenetic mechanism in complex neurological diseases such as autism spectrum disorder (ASD)." (PMID 41300647, 2025). "Since NLRP3 signaling is involved in various neurological disorders and the NLRP3 inflammasome is active in depressed patients, the NLRP3 inflammasome is a novel therapeutic target for the treatment of stress-induced depression." (PMID 40281288, 2025). "Ellagic acid (EA), a natural polyphenol with neuroprotective effects in neurological disorders, suppresses NLRP3 inflammasome signaling and proinflammatory cytokine release in microglia." (PMID 41415576, 2025). "Abnormal activation of inflammasome bodies in NOD‐, LRR‐, and pyrin domain‐containing protein 3 (NLRP3) microglia is also involved in the occurrence and development of various neurological diseases." (PMID 38915946, 2024). "The NLRP3 inflammasome plays a prominent role in neuroinflammation across a spectrum of neurological disorders." (PMID 39033121, 2024). "At present, neuro-inflammatory inhibitors have been widely explored as potential tools for treating neurological diseases, that mainly focus on these targets like TLRs, NF-κB, NLRP3 inflammasome, etc.." (PMID 37548945, 2024). "MCC950 has been found in reducing the progression of neurological diseases by suppressing the NLRP3 inflammasome." (PMID 38421496, 2024). "MLT has exerted anti-inflammatory effects by regulating NLRP3 inflammasome-related components in several neurological disorders." (PMID 36747075, 2023). "Inflammation mediated by NLR family pyrin domain containing 3 (NLRP3) inflammatory bodies is known to be closely related to nervous system diseases and can be activated by OS." (PMID 37261263, 2023). "Among these, the NLRP3 inflammasome is the most studied regulator of caspase-1 activation related to sterile inflammation in neurological diseases." (PMID 37353794, 2023). "In the pathogenesis of neurological diseases, NLRP3 inflammatory vesicle activation occurs mainly in microglia and macrophages." (PMID 38115996, 2023). "A total of 438 authors have participated in the research on the role of NLRP3 inflammasome in neurological diseases." (PMID 36160384, 2022). "Several compounds that interfere with the NLRP3 inflammasome pathway have shown therapeutic benefits in animal models and preclinical trials of neurological disorders." (PMID 36160384, 2022). "A better understanding of the underlying mechanisms regulating NLRP3 inflammasome will help us better evaluate the therapeutic potential of targeting NLRP3 inflammasome functions in neurological disorders." (PMID 36160384, 2022). "With the increasing research on inhibitors of NLRP3 specificity, NLRP3 inflammasome is also thought to be a potential drug target for treating neurological diseases." (PMID 36160384, 2022). "At present, more and more studies on neurological diseases have found that abnormal activation of NLRP3 inflammasome is involved in the occurrence and progression of diseases, and is mainly expressed in microglia and neurons." (PMID 36456961, 2022). "The importance of NLRP3 inflammasome in neurological diseases is widely appreciated, and the mechanism is under study." (PMID 36160384, 2022). "The most intensively studied inflammasome is NLRP-3, and it has been shown to be involved in many neurological diseases in adults." (PMID 35281473, 2022). "The third and fourth-ranked articles summarized the understanding of NLRP3 inflammasome in the genesis of neurological disorders." (PMID 36160384, 2022). "Although there are numerous protective effects of Dex among the neurological diseases, specific mechanisms including NLRP3 inflammasome-mediated neuroinflammation via oxidative stress response in a POCD model are not fully understood." (PMID 35955939, 2022). "Currently, NLRP3 inflammasome activation is under investigation in a wide range of neurological disorders." (PMID 36160384, 2022).
neurological diseases (continued). "It has been widely reported in the literature that NLRP3 inflammatory vesicles are extensively involved in the onset and development of aging and neurological diseases." (PMID 36046381, 2022). "Our study is the first bibliometric analysis of NLRP3 inflammasome in neurological diseases, but there are still some limitations." (PMID 36160384, 2022). "NLRP3/caspase-1 axis activation and pyroptosis have been shown to play vital roles in neuroinflammation and neuronal damage in various neurological disease models." (PMID 34666787, 2021). "In conclusion, autophagy plays an important role in the development and treatment of many nervous system diseases by affecting NLRP3 inflammasome." (PMID 34079796, 2021). "Further, NLR family pyrin domain-containing 3 (NLRP3)-mediated neuroinflammation plays a key role in neurological disorders including MDD." (PMID 33526073, 2021). "This article reviews NLRP3 inflammasome’s role in neurological diseases and related regulatory mechanisms, which providing references for future research in this field." (PMID 34526897, 2021). "NOD-like receptor protein 3 (NLRP3) inflammasome plays a significant role in both coordinating the host physiology and regulating the peripheral and central inflammatory responses in neurological diseases." (PMID 33916001, 2021). "Some studies have shown that NLRP3 inflammasome has been involved in many neurological diseases including chronic neurodegenerative disease." (PMID 34202695, 2021). "It is often necessary to consider the interaction of TXNIP and NLR family, domain of pyrin containing 3 (NLRP3) in neurological diseases." (PMID 34348577, 2021). "Current investigations have demonstrated that NLRP3 inflammasome–mediated cell death plays a critical role in the pathogenesis of multiple neurologic disorders, as well as SCI." (PMID 34899337, 2021). "We verified the inhibitory effect of P2X7R on the activation of microglia and the NLRP3 inflammasome in the mice model of CM, which was consistent with the results of other neurological diseases reported previously by other teams." (PMID 33402188, 2021). "Among the different types of NLRS, NLRP3 is the best-studied and characterized one because of its implications in different metabolic, autoimmune, and neurological disorders." (PMID 32604771, 2020). "NLRP3 activity in neurologic disorders is readily observed in microglia but our studies also revealed NLRP3 expression in surviving dopaminergic (DA) neurons of the mesencephalon in post-mortem tissues obtained from PD patients." (PMID 32680528, 2020). "In the following section, different examples of neurological disorders will be given and the role of the NLRP3 inflammasome in the development of these diseases will be presented." (PMID 31892810, 2019). "Altogether, these suggest that several inflammasomes, mostly in cooperation with NLRP3 or occasionally alone, have an important role in the physiopathology of neurological disorders." (PMID 31892810, 2019). "Investigation of NLRP3’s role in several neurological disorders reveals that excessive inflammatory signature observed in these pathologies is most often due to increased IL-1β levels in the brain and cerebrospinal fluid of patients." (PMID 31892810, 2019). "The relationship between NLRP3 and neurological disorders is an emerging field that needs further investigation." (PMID 31892810, 2019). "The NLRP3 inflammasome signaling pathway is a major contributor to the neuroinflammatory process in the nervous system disease." (PMID 30224927, 2018). "Aberrant activation of NLRP3 inflammasome signaling has been demonstrated to contribute to pathology in a broad spectrum of neurological diseases." (PMID 28337127, 2017).
neurological diseases (continued). "The NOD-like receptor protein 3 (NLRP3) inflammasome is important in the regulation of host physiology and neurologic disease The NLRP3 inflammasome plays an integral role in regulating peripheral and central inflammatory responses in host physiology and neurological disorders." (PMID 40770806, 2025). "Recent studies highlight the P2X7/NLRP3/IL-1β pathway in neurological diseases." (PMID 40732240, 2025). "These researches indicated that NLRP3 inflammasome might be a potential target for the treatment of neurological diseases." (PMID 37702910, 2024). "In summary, lncRNAs might reduce inflammation in neurological diseases by regulating autophagy to inhibit the production of pro-inflammatory mediators, activation of NLRP3 inflammatory vesicles and apoptosis." (PMID 37548945, 2024). "Among them, NLRP3 inflammasome has been extensively studied in different neurological diseases." (PMID 37063846, 2023). "With the use of bibliometric software CiteSpace, our study intends to present realistic and intuitive pictures of the evolutionary trends of research hotspots in the field, and to assist researchers in better understanding of the research dynamics on NLRP3 inflammasome in neurological diseases." (PMID 36160384, 2022). "Therefore, exploring the direct interaction between TXNIP and NLRP3 is essential for studying neurological diseases related to the ROS/TXNIP/NLRP3 signaling pathway." (PMID 35721021, 2022). "However, there are still some questions about the place of NLRP3 in pyroptosis in specific neurological diseases." (PMID 35937897, 2022). "Our research may provide potential targets for inhibitor development based on the ROS/TXNIP/NLRP3 signaling pathway, which may be useful for future therapeutic studies on neuroinflammation and related neurological diseases." (PMID 35721021, 2022). "Moreover, NLRP3 inflammasome is emerging as a promising therapeutic target in treating neurological disorders." (PMID 36160384, 2022). "Therefore, the inhibition of NLRP3 inflammasome activity has been suggested as a strategy for the treatment of neurological diseases." (PMID 35571246, 2022). "Top 10 high-cited references related to NLRP3 inflammasome in neurological diseases." (PMID 36160384, 2022). "At the same time, some studies have found that the overexpression of NLRP3 inflammasome is detected in the brains of patients with major degenerative neurological diseases, which is closely related to the occurrence and development of neurological diseases." (PMID 36262883, 2022). "Therefore, the present review provides an overview of natural extraction studies aimed at the prevention or treatment of NLRP3 inflammasome-mediated neurological disorders." (PMID 33525754, 2021). "NOD-like receptor protein 3 (NLRP3) inflammasome serves as an important player in both coordinating the host physiology and regulating the peripheral and central inflammatory responses in neurological diseases." (PMID 33916001, 2021). "Therefore, this review attempts to provide a new perspective and potential strategy for reducing the development and progression of neurological disorders through the regulation of natural products in the NLRP3 inflammasome." (PMID 33525754, 2021). "Previous studies have proved that decreasing ROS overproduction could prevent NLRP3 inflammasome activation and mitigate the elevated levels of proinflammatory cytokine release in different neurological disorders, thereby ameliorating neuroinflammation." (PMID 34777689, 2021). "Several studies report that the activation of the nucleotide-binding oligomerization domain leucine-rich repeat and pyrin domain-containing protein 3 (NLRP3) inflammasome, one of the most intensively investigated inflammasomes, is detrimental in neurological diseases, including PD." (PMID 34827148, 2021). "Thus, targeting the NLRP3/cleaved caspase-1/IL-1 axis has been a therapeutic strategy for neurological diseases." (PMID 34202695, 2021).